TRPM8 (transient receptor potential cation channel subfamily M member 8)
Diseases named in the same sentence as TRPM8 in open-access papers (continued):
Sharing a sentence is not in itself a finding about the gene and the disease.
prostate tumor (10 papers, 2012 to 2024). "Together our results indicate that the prostate tumor growth and development is associated with a complex androgen-TRPM8-AR regulatory loop." (PMID 25980497, 2015). "The mRNA encoding TRPM8 (transient receptor potential melastatin 8) is expressed in prostate tissues, and is upregulated in early prostate tumors." (PMID 25980497, 2015). "Bioluminescence based on the luciferase activity was measured weekly to follow PC3 cell growth, and we showed that the overexpression of TRPM8 inhibited prostate tumor growth." (PMID 35743115, 2022). "To investigate the role played by TRPM8 in prostate tumor growth, we performed an in vivo study using mice with a prostate orthotopic graft of PCa cells from bone metastases stably overexpressing (PC3–M8 luc) or not expressing (PC3 luc) the TRPM8 channel." (PMID 35743115, 2022). "Lastly, parallel TRPM8 immunostaining in primary prostate tumors and hormone naïve lymph node metastases collected from the same patient shows comparable amount of the channel." (PMID 33288740, 2020). "Transient Receptor Potential Melastatin 8 (TRPM8) is an ion channel from the thermoTRP family that was initially identified up regulated in prostate tumour cells." (PMID 28883526, 2017). "The TRPM8 mRNA is expressed in early prostate tumors with high androgen levels, while anti-androgen therapy greatly reduces its expression." (PMID 25980497, 2015). "More precisely, TRPM8 mRNA is overexpressed in well-differentiated early prostate tumors with high androgen levels, while anti-androgen therapy greatly reduces the expression of the protein." (PMID 25980497, 2015). "Taken together, the effects of TRPM8 on clonogenic cell ability and, to a lesser extent, cell proliferation may explain the inhibition of prostate tumor growth observed in vivo." (PMID 35743115, 2022). "In addition to its role in prostate tumor growth, TRPM8 was shown to inhibit PCa cell migration and invasion, leading to reduced prostate metastasis dissemination in mice." (PMID 35743115, 2022). "Indeed, we found that in mice grafted with luminescent PC3 cells overexpressing TRPM8, prostate tumor growth dramatically decreased starting 4 weeks after the orthotopic graft." (PMID 35743115, 2022). "Prostate tumors show in absolute the highest levels of TRPM8." (PMID 33288740, 2020). "TRPM8 mRNA was highly overexpressed in well-differentiated early prostate tumors." (PMID 23251635, 2012). "This evidence suggests that TRPM8 prevents prostate tumor growth by reducing the proliferation rate without inducing apoptosis." (PMID 35743115, 2022). "On the other hand, ectopic expression of TRPM8 in the AR− and TRPM8-non-expressing PC-3 cells produced a negative effect on the growth and progression of xenograft prostate tumor." (PMID 26512697, 2015). "TRPM8 had an effect on cell proliferation in prostate tumor cells but not in normal prostate cells." (PMID 35743115, 2022). "In addition, recent studies have demonstrated that the use of TRPM8 antagonists reduced the proliferation rates and proliferation fraction in all prostate tumour cells tested, but not in non-tumour cells." (PMID 28883526, 2017). "In prostate tumor tissues, TRPM8 mRNA is over-expressed relative to non-tumor tissues." (PMID 26512697, 2015).
uveal melanoma (10 papers, 2015 to 2025). A melanoma derived from melanocytes of the uveal tract. "In several cell lines, including uveal melanoma, endothelial, and corneal epithelial cells, activation of TRPM8 inhibited the VEGF transactivation of TRPV1 and the consequent pro-tumorigenic effects mediated by the VEGFR." (PMID 36768856, 2023). "Previous studies demonstrated the co-expression of TRPV1 with TRPM8 in different cell types including rat hippocampal neurons, intralobar pulmonary arteries, aorta, neuroendocrine tumor cells, retinoblastoma cells, uveal melanoma cells, and corneal cells." (PMID 30298050, 2018). "We found that TRPM8 is also overexpressed in highly malignant retinoblastoma and uveal melanoma along with TRPV1 compared to their levels in healthy human uvea or retina." (PMID 30483120, 2018). "Since the G protein-coupled cannabinoid receptor 1 (CB1) is expressed in uveal melanoma cells, we determined if either this receptor or its coupled G-proteins affect interactions between TRPM8 and TRPV1 in UM cells." (PMID 30483120, 2018). "In contrast, in human uveal melanoma cells, the gene expression of TRPM8 is at lower levels whereas the TRPA1 expression is at high levels in healthy uvea." (PMID 26818117, 2015). "In addition, TRPM8 is involved in calcium regulation in ocular tumors, such as uveal melanoma and RB cells." (PMID 38339011, 2024). "Furthermore, TRPV1 was upregulated in uveal melanoma cells suggesting that TRPM8 is a potential drug target for suppressing VEGF-induced increases in neovascularization and uveal melanoma growth." (PMID 36768856, 2023). "A similar suggestion was made for treating non-uveal melanoma (TRPM8)." (PMID 26818117, 2015). "Since TRPs like TRPV1 and TRPM8, as well as NGF receptors (TrkA), are (over)expressed in tumors such as uveal melanoma (UM) or retinoblastoma, we tested NGF on calcium regulation in human UM cells for comparison purposes." (PMID 40422222, 2025). "Functional TRPV1, TRPM8, and TRPA1 were also expressed in malignant human uveal melanoma tissues and cell lines." (PMID 34831352, 2021). "Another possibility for TRPM8 activation in tumor cells could be via the body’s own hormones, as has already been observed in uveal melanomas in connection with vascular endothelial growth factor (VEGF) and TRPM8 (thyronamine)." (PMID 38339011, 2024). "Therefore, it is suggested that identification of functional TRPV1, TRPM8, TRPA1 and CB1 expression in uveal melanoma may provide novel drug targets for treatment of this aggressive neoplastic disease." (PMID 26818117, 2015).
asthma (9 papers, 2008 to 2024). "It was discovered that the level of TRPM8 protein in asthma patients treated with bronchodilators was higher than in those without treatment." (PMID 38365763, 2024). "The contribution of TRPM8 rs11562975 SNP to the reduction in pulmonary function and the development of severe asthma have been demonstrated." (PMID 34356881, 2021). "Expression of TRPM8 was repeatedly reported to be upregulated in the respiratory tract of asthma and COPD patients both at mRNA and protein level." (PMID 33567636, 2021). "The role of synonymous SNP rs11562975 (p.Leu250=) of the TRPM8 gene in the formation of cold-induced airway hyperresponsiveness in asthma patients has been established." (PMID 34356881, 2021). "It has been revealed that TRPM8 expression is increased in the respiratory tract in patients with asthma." (PMID 34356881, 2021). "It has been established that sputum TRPM8 protein level is higher in asthma patients than in healthy subjects and significantly higher in bronchodilator-sensitive asthmatics than in nonresponders." (PMID 34356881, 2021). "Obviously, new methods for the treatment of asthma exacerbations caused by the influence of temperatures and humidity should be based on regulating the activity of TRPA1, TRPM8, and TRPV channels." (PMID 34356881, 2021). "In particular, TRP channels showing high levels of expression in sensory neurons such as TRPV1, TRPA1, and TRPM8, have been considered as targets for indications where sensory neurons play a fundamental role, such as pain, itch, and asthma." (PMID 31969645, 2020). "In addition, we replicated the effect of TRPM8 rs11562975 on lung function that was previously found in smoking asthma patients." (PMID 33567636, 2021). "If TRPM8 is involved in cold-induced asthma and asthma exacerbation, it would be interesting to know whether TRPM8 receptor expression is up-regulated in those people who are susceptible to asthma such that they are more sensitive to cold than normal subjects." (PMID 18534015, 2008). "Obviously, TRPM8 could be a molecular target for asthma therapy." (PMID 34356881, 2021). "Given the complexity and uniqueness of obese asthma, we have identified three TRP channels – TRPV1, TRPM8, and TRPC1 – and examined their role in immune cells, particularly macrophages." (PMID 38365763, 2024). "Activating TRPM8 on adipose tissue cells can control the secretion of leptin and ADPN, reduce the levels of adipocytokines that promote airway inflammation, and help suppress asthma." (PMID 38365763, 2024). "Due to the high expression of certain TRP channels, particularly in immune cells like macrophages, and the findings from previous research, as well as their clear or potential involvement in the inflammatory process of obese asthma, we have specifically chosen to discuss TRPV4, TRPM8, and TRPC1." (PMID 38365763, 2024). "Moreover, the role of TRPM8 in the induction of inflammation, mucus hypersecretion, and airway remodeling in asthma patients even in the absence of the influence of irritants has been reported." (PMID 34356881, 2021).
Hypertension (9 papers, 2018 to 2024). The presence of chronic increased pressure in the systemic arterial system. "TRPM8 was also linked to other pain types or discomfort states such as irritable bowel syndrome, oropharyngeal dysphagia, and chronic cough, as well as to inflammatory processes of the respiratory tract, and hypertension." (PMID 34445208, 2021). "Activation of the RAA system via TRPM8 plays a crucial role, leading to hypertension, increased plasma Ig levels, and subsequent immunosuppression, including impaired bacterial clearance." (PMID 39273376, 2024). "ISIAH (inherited stress-induced arterial hypertension) rats are characterized by high blood pressure and decreased Trpm8 gene expression in the anterior hypothalamus." (PMID 35682765, 2022). "Undoubtedly, comprehensive research studies of TRPM8 open up new opportunities in findings of optimal natural impacts on the organism (by temperature or by natural plant component) to combat hypertension." (PMID 35682765, 2022). "The results obtained in this study, together with the data provided during their discussion, indicate the important value of TRPM8 both in the elevation of blood pressure and in metabolic changes that can provoke hypertension as a metabolic disease." (PMID 35682765, 2022). "In the meanwhile, the feasibility of targeting Ca2+ channels has already been highlighted by clinical experience of voltage gated Ca2+ channel blockers for the treatment of hypertension, and also by the viable phenotype of TRPM8−/− mice." (PMID 35361751, 2022). "In summary, the results of this study revealed that TRPM8 is a critical upstream regulator for eliciting cold exposure–induced RAAS-mediated hypertension." (PMID 29560109, 2018). "TRPM8, as a cold sensor, may alleviate cold-induced hypertension related to the renin–angiotensin–aldosterone system by inhibiting Ang II-induced cytoplasmic Ca2+influx and mitochondrial calcium overload after being activated by menthol." (PMID 38255767, 2024). "Cold-induced IgG elevation and subsequent immunosuppression are mediated through the activation of the renin–angiotensin–aldosterone (RAA) system via transient receptor potential melastatin 8 (TRPM8), leading to hypertension and impaired bacterial clearance in vivo." (PMID 39273376, 2024). "Furthermore, the thermosensitive receptors, TRPA1/TRPM8/TRPV1, which are expressed in the cardiovascular system, have been implicated in the pathogenesis of hypertension." (PMID 38255767, 2024). "TRPM8 channels have been implicated also in oropharyngeal dysphagia and chronic cough, while the downregulation of TRPM8 by angiotensin II may be involved in hypertension." (PMID 32751347, 2020). "Another evidence of a TRPM8 interplay with small GTPases in controlling ECs behavior comes from a study of Sun and coworkers, which has revealed a role of TRPM8 in vasoconstriction and hypertension through attenuating RhoA/Rho kinase pathway." (PMID 33132914, 2020). "Main results indicated that TRPM8 activation benefits both vascular function and blood pressure, through inhibiting Ca2+ signaling-mediated RhoA/Rho kinase activation in blood vessels, suggesting that long-term dietary menthol treatment could have favorable effects on hypertension." (PMID 34445208, 2021). "Here we found that cold exposure leads to transient receptor potential melastatin 8 (TRPM8)-dependent, renin–angiotensin–aldosterone system (RAAS)-mediated hypertension, which subsequently induces small molecule and fluid extravasation, increases plasma Ig levels, and elicits immunosuppression." (PMID 29560109, 2018). "The TRPM8 channels have attracted increasing attention in the past decade as promising drug targets for treatment of different pathologic processes, such as colonic inflammation, dry eye disease (DED), tumors, oropharyngeal dysphagia, chronic cough, and hypertension." (PMID 32751347, 2020).
neuropathic pain (9 papers, 2011 to 2025). Chronic pain caused by damage to nerve fibers. "Several lines of evidence indicated that the TRP channels i.e., vanilloid 1 (TRPV1) and melastatin 8 (TRPM8) play a pivotal role in chemotherapy-induced neuropathic pain." (PMID 34199936, 2021). "On a higher level of nociceptive processing, in the spinal dorsal horn, input from TRPM8-expressing cutaneous primary afferents (“cold fibers”) seems to exert antinociceptive, gate-controlling, effects in an animal model of neuropathic pain." (PMID 26207981, 2015). "Although most studies of TRPM8 and allodynia have been focused on the cold allodynia, the involvement of TRPM8 in mechanical allodynia has been reported in multiple inflammatory and neuropathic pain conditions." (PMID 34149356, 2021). "Discrepancies in neuropathic pain model and the level of TRPM8 expression may be the reasons for this inconsistence." (PMID 22111979, 2011). "An abundance of research has documented elevated expression levels of TRPM8 (transient receptor potential melastatin 8) in the spinal cord and DRG of neuropathic pain animal models, positing TRPM8 as a promising therapeutic target." (PMID 40264787, 2025). "In the oxaliplatin-induced model of neuropathic pain, neurons are directly affected by OXPT, which induces central and peripheral sensitization as a consequence of upregulation of TRPM8 and TRPA1 and downregulation of Kv4.3 neuronal channels." (PMID 37895952, 2023). "To further strengthen the participation of the spinal TRPV1/TRPM8/P2Y receptors in the development of VCR-induced neuropathic pain, we measured the protein expression of the TRPV1/TRPM8/P2Y receptors using immunohistochemistry." (PMID 34199936, 2021). "There results suggest that TRPM8 and membrane depolarization in IB4– neurons might serve as the initial ionic/membrane drives that contribute to the development of oxaliplatin-induced neuropathic pain." (PMID 34149356, 2021). "Our results suggest that TRPM8 and TRPM8-mediated membrane depolarization, but not TRPA1 or TRPV1, serve as the initial ionic/membrane drives that contribute to the development of oxaliplatin-induced neuropathic pain." (PMID 34149356, 2021).
esophageal cancer (8 papers, 2019 to 2024). A primary or metastatic malignant neoplasm involving the esophagus. "In esophageal cancer, TRPM8 has been implicated in promoting tumor cell proliferation and immune evasion." (PMID 39062591, 2024). "Elucidating the regulatory mechanisms of TRPM8 in esophageal cancer holds promise for advancing the diagnosis and management of this disease." (PMID 39062591, 2024). "Esophageal cancer is another malignant tumor of the digestive system with a high incidence and mortality; in this kind of tumor, TRPM8 channels have an important effect in promoting cell viability and avoiding apoptosis." (PMID 37033630, 2023). "In esophagus cancer, TRPM8 mediates the activation of the calcineurin-NFATc3 signaling pathway, which stimulate the increase in PD-L1 expression." (PMID 37033630, 2023). "Meanwhile, mRNA and protein expression of another melastatin TRP channel, TRPM8, was shown to be upregulated in esophageal cancer cells compared to adjacent normal tissue." (PMID 35562940, 2022). "In parallel, TRPM8-calcineurin-induced NFATc3 activation was involved in the pathogenesis of esophageal cancer as we proved." (PMID 31519770, 2019). "In the current work, we found that TRPM8 was overexpressed in esophageal cancer samples and cell lines." (PMID 31519770, 2019). "The cytological experiments showed that both TRPM8 knockdown and TRPM8 antagonist inhibited proliferation of esophageal cancer cells, and TRPM8 overexpression and TRPM8 agonist exerted the opposite role." (PMID 31519770, 2019). "Our results showed that blocking the activity of calcineurin inhibited the nuclear translocation of NFATc3 and PD-L1 expression in esophageal cancer cells, which inferred a contributing role of TRPM8-calcineurin-NFATc3 in the expression of PD-L1." (PMID 31519770, 2019). "In this research, we discovered the pro-tumor role of TRPM8 in the pathogenesis of esophageal cancer." (PMID 31519770, 2019). "Next, the co-incubation assay including EC109 cells and CD8+ T cells revealed that TRPM8 overexpression and TRPM8 agonist reduced the cytotoxic effect of CD8+ T cell on esophageal cancer cells." (PMID 31519770, 2019). "In summary, our research verified the potential role of TRPM8 in proliferation and immune evasion of esophageal cancer, and provided a novel mechanism in the pathogenesis of esophageal cancer." (PMID 31519770, 2019). "Next, we performed the following experiments in EC109 cells to investigate the biological effect of TRPM8 on esophageal cancer cells." (PMID 31519770, 2019). "TRPM8 inhibition by genetic and pharmacological intervention suppressed proliferation of esophageal cancer cells, and increased cell apoptosis." (PMID 31519770, 2019). "To further verify the proliferative role of TRPM8 in esophageal cancer cells, we performed colony formation assay." (PMID 31519770, 2019). "To investigate the biological effect of TRPM8 on the development and progression of esophageal cancer, we first evaluated the expression of TRPM8 in clinical specimens and cell lines of esophageal cancer." (PMID 31519770, 2019). "For example, TRPM8-mediated proliferation has been observed in esophageal cancer cell lines." (PMID 39150496, 2024). "PD-L1 has been proposed as a prognostic predictor for human esophageal cancer, and modulating TRPM8 channel activity with antagonist could be a pharmacological strategy to regulate PD-L1 effects in esophageal cells." (PMID 37033630, 2023). "The knockdown and inhibition of TRPM8 decrease proliferation of esophageal cancer cells." (PMID 32182937, 2020). "In our work, the results displayed a pro-tumor role of TRPM8 in esophageal cancer." (PMID 31519770, 2019). "First, we found TRPM8 was up-regulated in esophageal cancer." (PMID 31519770, 2019). "Further investigation revealed that TRPM8 promoted proliferation of esophageal cancer cells." (PMID 31519770, 2019).